Y_RNA (Y RNA )
Gene: Miscellaneous RNA gene on chromosome 1 (25,877,496 to 25,877,605, forward strand). Ensembl gene ENSG00000207302.
Homologues: Orthologues: chimpanzee Y_RNA (100% identical), macaque Y_RNA (95% identical). Paralogues in human: Y_RNA (81% identical), RNY1P5 (80% identical), Y_RNA (80% identical), Y_RNA (79% identical), Y_RNA (78% identical), Y_RNA (77% identical), Y_RNA (76% identical), Y_RNA (75% identical), RNY1P6 (75% identical), RNY1 (74% identical), Y_RNA (74% identical), RNY1P11 (73% identical), and 93 more.